COPDA1 (chronic obstructive pulmonary disease associated lncRNA 1)
Synonyms: RP11-731F5.2
Gene: Long non-coding RNA gene on chromosome 14 (105,647,924 to 105,649,057, reverse strand). Ensembl gene ENSG00000253364.
Diseases named in the same sentence as COPDA1 in open-access papers:
COPDA1 is named in the same sentence as 2 diseases in open-access papers, as found by Europe PMC text mining. Sharing a sentence is not in itself a finding about the gene and the disease. The quoted sentences say what the papers report.
melanoma (2 papers, 2025). A malignant, usually aggressive tumor composed of atypical, neoplastic melanocytes. "LINC02132 and COPDA1 can influence the proliferation, invasion, migration, and apoptosis of melanoma." (PMID 40092985, 2025). "To further investigate the effect of LINC02132 and COPDA1 on the apoptosis of melanoma cells, we transfected the overexpression plasmid through flow cytometry." (PMID 40092985, 2025). "The results demonstrated that both LINC02132 and COPDA1 influence the proliferation, migration, and invasion of melanoma cells." (PMID 40092985, 2025). "Compared to the melanoma cell group, expression of COPDA1, LINC02132, and LINC02812 in the cytoplasm was elevated in the normal skin group." (PMID 40092985, 2025). "We can also investigate the specific regulatory mechanisms of LINC02132 and COPDA1 on melanoma cell apoptosis in future experiments." (PMID 40092985, 2025). "Our findings suggest that upregulation of the LINC02132 or COPDA1 genes elevates intracellular reactive oxygen species (ROS) levels in melanoma cells, suppresses tumor cell proliferation, migration, and invasion, and promotes apoptosis." (PMID 40092985, 2025). "We then validated the verifiable genes, LINC02132 and COPDA1, in two melanoma cell lines and clinical tissues." (PMID 40092985, 2025). "We observed that melanoma cells overexpressing LINC02132 and COPDA1 had an increased number of apoptotic cells compared with the control group." (PMID 40092985, 2025). "In order to further verify the effect of LINC02132 and COPDA1 genes on the migration and invasion of melanoma cells, we performed scratch assay and transwell invasion and invasion assay, and the results showed that LINC02132 and COPDA1 could reduce the migration and invasion of melanoma cells." (PMID 40092985, 2025).
COPDA1 also shares sentences with these, for which no sentence is quoted: Tumor (1 paper).